GPER1 (G protein-coupled estrogen receptor 1)
Diseases named in the same sentence as GPER1 in open-access papers (continued):
Sharing a sentence is not in itself a finding about the gene and the disease.
breast carcinoma (continued). "Previous reports have shown an increased translocation of GPER-1 to the cell surface of MCF-7 breast cancer cells that were continuously exposed to 10 nM tamoxifen for 6 months and stimulated with 17β-estradiol." (PMID 33117280, 2020). "Analysis of data from a subset of breast cancer patients has shown that GPER-1 expression has also been positively correlated with overexpression of EGFR." (PMID 33117280, 2020). "Thereby, the use of tamoxifen on breast cancer patients with initial GPER-1 positive tumors increased GPER-1 protein expression and markedly reduced survival." (PMID 33117280, 2020). "Here we have corroborated that GPER-1 is overexpressed in breast cancer cells exposed for 7 days to 1,000 nM tamoxifen, a concentration similar to that found in breast tissue of patients treated with this drug." (PMID 33117280, 2020). "Together our findings suggest that GPER-1 plays a key role in the mechanisms of tamoxifen resistance of estrogen-sensitive breast cancer cells, extending the limits of understanding of the effects generated by tamoxifen in these cells." (PMID 33117280, 2020). "MCF-7 breast cancer cells were continuously treated with 1,000 nM tamoxifen for 7 days to investigate its effect on GPER-1 protein expression, cell proliferation and intracellular [Ca2+]i mobilization, a key signaling pathway." (PMID 33117280, 2020). "It has recently been shown that stimulation with tamoxifen, activates GPER-1, improving breast cancer stem cells viability and stemness and BAD phosphorylation, event that seems to be an alternative survival mechanism for these cells." (PMID 33117280, 2020). "The identification of new agonists has largely occurred in breast cancer cell lines that endogenously express GPER1." (PMID 33281743, 2020). "In breast cancer cells, it was observed that oncogenic estrogenic G-protein-coupled estrogen receptor-1 (GPER) signaling pathway decreased downstream miR-148a level, further contributing to cancer immune evasion." (PMID 32222150, 2020). "These compounds exhibited a similar effect on breast cancer proliferation as reported in the literature in response to the GPER1-selective agonist, G-1." (PMID 33281743, 2020). "More recently, it has been shown that in ER-negative and GPER1-positive breast cancer cells, E2 is able to modulate the expression of diverse miRNAs." (PMID 33374170, 2020). "Here, the current knowledge about GPER1 and miRNA action in breast cancer is recapitulated, reporting recent evidence on the liaison of these two players in triggering breast tumorogenic effects." (PMID 33374170, 2020). "Although we cannot fully extrapolate the results obtained in vitro to the patients, this cell line is a good example of those mammary tumors made up of cells that express both ERα and GPER-1." (PMID 33117280, 2020). "Collectively, our data revealed a novel mechanism that regulates GPER1 expression resulting in altered sensitivity of breast cancer cells to tamoxifen." (PMID 31242463, 2019). "In this study, GPER1 expression was significantly induced upon D-glucose deprivation in tamoxifen-sensitive breast cancer cell lines and the observed increase in GPER1 expression was AMPK-dependent." (PMID 31242463, 2019). "We previously reported that 4-hydroxytamoxifen (Tam), the active metabolite of tamoxifen, induces the expression of IGFBP-1 in a GPER1-dependent manner in MCF-7 breast cancer cells." (PMID 31242463, 2019). "Results reported herein reveal that GPER1 expression in breast cancer cells is sensitive to [D-glucose] and requires AMPK-dependent signaling." (PMID 31242463, 2019). "The recently identified GPER1-dependent mechanism of tamoxifen action in breast cancer cells underscores the importance of identifying mechanisms that regulate GPER1 expression in this cell type." (PMID 31242463, 2019). "Two recent studies demonstrated that low dose phthalates activate GPER1, resulting in increased proliferation of breast cancer cells and cervical cancer cells." (PMID 31861598, 2019).
breast carcinoma (continued). "In ER negative breast cancer cells, activating GPER-1 by an agonist such as G1, led to cell cycle arrest and apoptosis suggesting GPER-1 as a promising target for breast cancer therapy." (PMID 31749762, 2019). "The impact that [D-glucose] had on GPER1-dependent tamoxifen action in breast cancer cells was demonstrated by measuring the accumulation of IGFBP-1 expression in tamoxifen-treated breast cancer cells in the presence of increasing [D-glucose]." (PMID 31242463, 2019). "Due to the important role that GPER1 has in breast cancer cell biology and treatment outcomes, it is important to understand the molecular determinants of GPER1 expression in this cell type." (PMID 31242463, 2019). "The other evidences also approved that GPER-1 is an initiator of tamoxifen resistance in breast cancers." (PMID 27314054, 2016). "G-protein-coupled estrogen receptor-1 is widely expressed in breast cancer cell lines and breast primary tumors." (PMID 24834064, 2014). "This is in agreement with our recent results demonstrating that GPER-1 cross-talks with EGFR in breast cancer cell lines." (PMID 23849542, 2013). "We have found that GPER-1 is inactivated via promoter methylation in breast cancer tissue and is re-expressed after treatment with de-methylating agent 5-Aza (own not published data)." (PMID 23849542, 2013). "It is known that the new membrane-bound estrogen receptor GPER-1 acts suppressive in breast cancer cells and its expression decreases during disease progression." (PMID 23849542, 2013). "It is important to note that Tamoxifen, a major estrogen selective modulator for breast cancer treatment, has been identified as an agonist of GPER1." (PMID 23285198, 2012). "Indeed, both miR-339 and the tumor suppressor gene GPER1 are differentially downregulated in distinct breast cancer subtypes." (PMID 40149701, 2025). "Thus, for example, continuous exposition to tamoxifen, the first-line drug against estradiol-sensitive breast cancer, overexpresses GPER-1, increasing calcium mobilization and cell proliferation." (PMID 39936103, 2025). "GPER-1 activation complexly modulates the expression of multiple microRNAs in breast cancer." (PMID 39936103, 2025). "Importantly, transfection of miR-339 specifically re-activates GPER1 expression by interacting with its enhancer, thereby inhibiting the proliferation of breast cancer cells." (PMID 40149701, 2025). "Estrogen, a key hormone, plays a pivotal role in driving the progression of breast cancer through its interaction with three receptors: estrogen receptor α (ERα), estrogen receptor β (ERβ), and G-protein coupled estrogen receptor 1 (GPER-1), as well as estrogen-related receptors (ERRs)." (PMID 41200178, 2025). "Suggesting an inverse relation between DNA methylation and GPER-1 expression in breast cancer." (PMID 39936103, 2025). "Interestingly, breast cancer cell lines that express GPER-1 showed hypomethylation of this CpG island." (PMID 39936103, 2025). "Moreover, loss of NamiRNA‐339 directly induced the downregulation of tumor suppressor genes including YAP1, DUSP6, and GPER1, and thus promoted the development of breast cancer." (PMID 38585233, 2024). "The acute and non-genomic effects of estrogens, such as rapid vascular effects, are mediated partly by G protein-coupled estrogen receptor 1 (GPER), which was initially cloned as GPR30, an orphan receptor differentially expressed in estrogen-responsive breast cancer cell lines by multiple groups." (PMID 39273478, 2024). "Upon treatment with Ful, IGFBP-3 was induced in breast cancer cells similar to data observed in reports describing the regulation of IGFBP-1 by the G-protein-coupled estrogen receptor (GPER1) and clinical studies showing IGFBP-3 serum increases in response to Ful." (PMID 39619437, 2024). "Compared to normal tissues, GPER1 is detected with a higher expression in breast cancer cells." (PMID 37835383, 2023).
breast carcinoma (continued). "Likewise, in breast carcinoma, a correlation has been observed between high GPER1 expression, increased cell proliferation, invasion, migration, and worsened prognosis." (PMID 37762008, 2023). "Prior to conducting experiments to determine whether G-1 and 2-MeO-E2 negatively affected the proliferation of LTED and MCF-7 cells by targeting GPER1, we confirmed the expression profile of GPER1 in these breast cancer cells." (PMID 37754248, 2023). "However, additional studies have reported that GPER1 inhibits breast cancer proliferation, progression and tumour angiogenesis." (PMID 37921845, 2023). "GPER1 is a membrane-type receptor discovered in 1996 in breast cancer tissue." (PMID 37754248, 2023). "GPER1 is thought to play a favorable role against breast cancer." (PMID 36060947, 2022). "The positive correlation between expressions of ERs and GPER1 are consistent with previous findings in breast cancer, which might be explained by a report that E2-stimulated upregulation of GPR30 is ERs-dependent(s)." (PMID 35664735, 2022). "Because gene change is an early event of toxicity response, these findings suggested that BPAF might aggravate the condition of breast cancer patients through exerting its estrogenic activity via the GPER1 pathway in various organs." (PMID 36497816, 2022). "In breast cancers, signalling of membrane-bound G-Protein-coupled estrogen receptor 1 (GPER) through transactivation of EGF-R could also be inhibited by GnRH-agonist treatment." (PMID 33535622, 2021). "In addition, estrogen can intervene in autophagy and the growth of breast cancer cells via GPER1, which makes GPER1 a potential therapeutic target to treat TNBC." (PMID 34768896, 2021). "However, the role of GPER1 in the biology of breast cancer and its clinical significance is far from being understood, and contradictory results regarding its localization and actions in relation to the classic estrogen receptors have been reported." (PMID 34299224, 2021). "Therefore, although we knew that GPER1 plays a role in some forms of breast cancer, its implication in inflammatory mechanisms (as reported here), including cancer-related inflammation, opens interesting new perspectives." (PMID 34299224, 2021). "Elucidating the role of GPER1 and miRNAs in breast cancer might provide new tools for innovative approaches in anti-cancer therapy." (PMID 33374170, 2020). "Although we cannot fully extrapolate the results obtained in vitro to the patients, our results shed some light on the occurrence of drug resistance in breast cancer patients who are ERα/GPER-1 positive, have been treated with tamoxifen and display low survival rate." (PMID 33117280, 2020). "GPER1 has been detected in about 50 to 60% of breast cancer tissues." (PMID 33374170, 2020). "Since, a cooperative effect or association between GPER-1 and kinin B1R in breast cancer has not been explored yet; a next set of experiments should be focused on the role of both receptors in breast cancer patients." (PMID 33117280, 2020). "Although the mechanisms of resistance in estrogen-sensitive breast cancer are probably multifactorial, our evidence indicates that at least part of the phenomenon may be due to overexpression and activation of GPER-1." (PMID 33117280, 2020). "GPER1 activation is now well-known for inducing protective effects in several disease models, including I/R injury, hypertension, Parkinson's disease, retinal ganglion degeneration, and breast cancer." (PMID 33193095, 2020). "Notably, silencing of GPER-1 inhibited the positive regulation of Cav1.3 induced by estrogen, reversing the increase in intracellular calcium release and proliferation of breast cancer cells." (PMID 33117280, 2020).
breast carcinoma (continued). "In breast cancer cells, GPER1 actions have been found to stimulate key regulators of the evolutionarily conserved Hippo pathway that involves the yes-associated protein 1 (YAP) and transcriptional coactivator with a PDZ-binding domain (TAZ), which are homologous transcription coactivators." (PMID 33193095, 2020). "Breast cancer cells continuously treated with tamoxifen, exhibited a robust [Ca2+]i mobilization after stimulation with 1,000 nM tamoxifen, a response that was blunted by preincubation of cells with G15, a commercial GPER-1 antagonist." (PMID 33117280, 2020). "This suggests that the Hippo/YAP/TAZ pathway might be a key downstream signaling pathway of GPER1 long-term actions, especially in breast cancer tumorigenesis." (PMID 33193095, 2020). "Based on these data, we hypothesized that [D-glucose]-dependent changes in GPER1 expression alter the IGFBP-1-dependent tamoxifen response of breast cancer cells." (PMID 31242463, 2019). "Taken together, this study revealed a previously unknown mechanism that regulates GPER1 expression in ERα positive breast cancer cells and alters sensitivity to tamoxifen treatment." (PMID 31242463, 2019). "Our previous work identified GPER1 as a key mediator of tamoxifen action in breast cancer cells leading to the hypothesis that GPER1 expression is sensitive to [D-glucose] and changes in GPER1 expression alters the tamoxifen response in breast cancer cells." (PMID 31242463, 2019). "Analysis of GPER1 expression in 361 human breast carcinomas revealed that unlike nuclear ERs, GPER1 expression showed a positive association with HER-2/neu status, tumor size, and metastasis." (PMID 31861598, 2019). "We hypothesized that GPER1 expression in breast cancer cells is sensitive to [D-glucose] and provide data showing increased GPER1 expression when cells were cultured in low [D-glucose]." (PMID 31242463, 2019). "Taken together, these results identify a previously unknown mechanism that regulates GPER1 expression that modifies one aspect tamoxifen action in breast cancer cells." (PMID 31242463, 2019). "GPER-1 is widely expressed in both of these breast cancer types and the primary breast cancers." (PMID 27314054, 2016). "Paradoxical debates still exist on the functions of GPER-1 in breast cancers." (PMID 27314054, 2016). "Interestingly, GPER-1 preformed a different proliferation manner in ER positive MCF-7 breast cancer cell line." (PMID 27314054, 2016). "Thus, GPER1 has been shown to increase cyclic AMP levels by the activation of adenylyl cyclase in human breast cancer cell lines, such as SKBR3, which lack ERα and ERβ and in transfected human embryonic kidney 293 cells." (PMID 26998610, 2016). "Thus, GPER-1 inhibits ER positive breast cancers proliferation which is a potential target for ER positive breast cancers and drug-resistant breast cancer." (PMID 27314054, 2016). "We postulated that GPER1 might play the important roles in inhibitory effect of E2 on the n-3 PUFA-treated breast cancer cell growth." (PMID 23285198, 2012). "Hence, estrone, by acting as a GPER-1 agonist, could contribute to the development of estrogen-sensitive breast cancer." (PMID 39936103, 2025). "Interestingly, GPER-1 also interacts with molecules that exhibit structural homology with estradiol, which could contribute to breast cancer development and its relation to environmental pollution." (PMID 39936103, 2025). "Our data suggest that kinin B1R overexpression is an early event and that together with GPER-1 it may be part of a cross-talk network in estrogen-sensitive breast cancer cells to enhance cell proliferation and/or metastasis by activating signaling mechanisms, which are independent of ERα." (PMID 33117280, 2020). "Furthermore, GPER-1 agonist G-1 promoted inflammation in breast cancers." (PMID 27314054, 2016).
breast carcinoma (continued). "Multiple GPCRs have been extensively associated with cancer, for example, the thyrotropin receptor in thyroid adenomas, estrogen receptors GPER1 and GPR30 in breast cancer, and gonadotropin-releasing hormone receptor GnRH in prostate cancer." (PMID 38612509, 2024). "First, SKBR-3 breast cancer cells, which endogenously express GPER1, and HEK293T cells transfected to express GPER1 exogenously were shown to bind to radioactive estrogen." (PMID 37947649, 2023). "In breast cancer cells, 4-OHT suppresses IGF-1 signaling due to the accumulation of extracellular IGFBP1, which is mediated by GPER1 and CREB." (PMID 37907850, 2023). "GPER1, a member of the G protein-coupled receptor (GPCR) family, also known as GPR30, was first identified in 1996 in breast cancer tissues and was initially termed GPCR-Br." (PMID 37762356, 2023). "In breast cancer, it has been shown that HIF-1α, in concert with G protein-coupled estrogen receptor 1 (GPER), transcriptionally upregulates VEGF expression in hypoxic CAFs to promote endothelial tube formation." (PMID 35884382, 2022). "In addition, at a translational level, our findings are in line with reports that the low expression of GPER1 in breast cancer is related to adverse patient survival, while several in vitro experiments have found that it can attenuate the growth of ER-positive breast cancer cell lines." (PMID 34299224, 2021). "GPER, also named GPER1 or GPR30, is a transmembrane intracellular receptor and is found highly expressed on some breast cancer tissue and cell lines." (PMID 34445359, 2021). "The stimulation of GPER1 activates Ca2+ release, ERK1/2, PI3K action and stimulation of epidermal growth factor receptor (EGFR) transcription in breast cancer cell lines." (PMID 34089761, 2021). "In breast cancer cells, the Hippo/YAP/TAZ pathway has been reported as a key downstream signaling branch of GPER1 actions and plays a critical role in breast tumorigenesis." (PMID 33193095, 2020). "This is an interesting mechanism since in the same study GPER1 was also found to be upregulated by EGF and TGF alpha in endometrial and tamoxifen-resistant breast cancer cells via the EGFR/ERK transduction pathway and c-fos." (PMID 33133022, 2020). "The silencing of G protein-coupled estrogen receptor 30 (GPER1/GPR30) mediated via siRNA transfection abolished Ca2+-influx as well as proliferation in BC, which may be an indication of a crucial role of Ca2+ entry through L-type channels in cell proliferation and breast cancer progression." (PMID 31226817, 2019). "In the tumor microenvironment, GPER-1 activation also activates HIF-1-α dependent pathways aiding in angiogenesis and progression of breast cancer." (PMID 31749762, 2019). "Previously, we showed that 4-hydroxytamoxifen (Tam) induces the expression of insulin-like growth factor-binding protein 1 (IGFBP1) via a GPER1-dependent mechanism in MCF-7 and SkBr-3 breast cancer cells." (PMID 31242463, 2019). "G-protein-coupled estrogen receptor-1 (GPER, formerly known as GPR30) has attracted increasing interest, considering its ability to mediate estrogenic signaling in breast cancer." (PMID 25928008, 2015). "The GPR30, also known as GPER1, is a former orphan GPCR that was shown to bind 17β-E and increase cAMP in breast cancer SKBR3 cells via an increase in adenylyl cyclase activity." (PMID 25762980, 2015). "Although the involvement of GPER1 in the control of Notch1-HES1 signaling was reported in breast cancer cell lines, we have found no direct role of GPER1 in regulating the activity of Notch pathway in SC." (PMID 40506655, 2025).